PIEZO1 (piezo type mechanosensitive ion channel component 1 (Er blood group))
Diseases named in the same sentence as PIEZO1 in open-access papers (continued):
Sharing a sentence is not in itself a finding about the gene and the disease.
Crohn disease (2 papers, 2023). A gastrointestinal disorder characterized by chronic inflammation involving all layers of the intestinal wall, noncaseating granulomas affecting the intestinal wall and regional lymph nodes, and transmural fibrosis. "PIEZO1 is highly expressed in patients with active Crohn’s disease and is positively correlated with Crohn’s disease activity index and fecal calprotectin levels." (PMID 38130953, 2023). "Initiation of proinflammatory responses in the intestine likely involves Piezo1, which is highly expressed in the ileum of patients with Crohn’s disease and positively correlates with the Crohn’s Disease Activity Index and fecal calprotectin levels." (PMID 37781915, 2023). "PIEZO1 in intestinal epithelial cells mediates the inflammation in Crohn’s disease through the NLRP3 pathway." (PMID 38130953, 2023).
demyelinating disease (2 papers, 2023 to 2025). A broad group of disorders that affect the myelin sheaths that cover the neurons. "PIEZO1 plays a crucial role in mechanical sensation within the central nervous system, and its dysfunction may be associated with the onset and progression of various neurological disorders, including demyelinating diseases." (PMID 40703567, 2025). "In recent years, numerous studies have suggested that PIEZO1 is a promising therapeutic target for demyelinating diseases." (PMID 40703567, 2025). "By targeting its structure, gene expression, or involvement in signaling pathways, these approaches have the potential to address the pathological processes involving PIEZO1 in demyelinating diseases at a more fundamental level." (PMID 40703567, 2025). "Future research is expected to further elucidate the specific mechanisms of PIEZO1 in demyelinating diseases." (PMID 40703567, 2025). "More studies are needed to explore how PIEZO1 can be targeted for therapeutic intervention, paving the way for novel treatments for demyelinating diseases." (PMID 40703567, 2025). "The article introduces the concepts, classifications, and etiologies of demyelinating diseases while highlighting PIEZO1’s role in the nervous system, particularly in myelin development and formation." (PMID 40703567, 2025). "This article aims to review the current research on the role of Piezo1 in myelination and its involvement in demyelinating diseases, as well as to explore the potential of targeting Piezo1 for therapeutic interventions in such conditions." (PMID 40703567, 2025). "Investigating the structure, gene expression, or signaling pathways of PIEZO1 may serve as valuable research directions, providing new insights and strategies for the treatment of demyelinating disorders." (PMID 40703567, 2025). "This article reviews PIEZO1, demyelinating diseases, and the role of PIEZO1 in these conditions." (PMID 40703567, 2025). "Therefore, identifying alternative PIEZO1 modulators with improved pharmacological efficacy is crucial for advancing targeted therapies for demyelinating diseases." (PMID 40703567, 2025). "Finally, it explores the therapeutic potential of targeting PIEZO1 in demyelinating diseases and its implications for expanding treatment strategies." (PMID 40703567, 2025). "In summary, PIEZO1 plays a pivotal role in demyelinating diseases, and its inhibition or activation may hold significant therapeutic and neuroprotective potential." (PMID 40703567, 2025). "Therefore, we hypothesize that in demyelinating diseases, activation of Piezo1 due to a rigid matrix activates YAP and promotes its nuclear translocation, thereby inhibiting oligodendrocyte‐mediated myelin regeneration." (PMID 37366640, 2023). "Notably, studies have shown that pharmacological activation of PIEZO1 channels can induce demyelination while blocking PIEZO1 channels can prevent axonal and myelin damage in the CNS and also alleviate secondary progressive neurodegeneration following demyelinating diseases." (PMID 40703567, 2025).
dilated cardiomyopathy (2 papers, 2021 to 2023). Cardiomyopathy which is characterized by dilation and contractile dysfunction of the left and right ventricles. "In the human diseased hearts, the RNA-sequencing data from human failing hearts with dilated cardiomyopathy (DCM) (GEO accession no: GSE29819) showed that the mRNA level of Piezo1 was up-regulated in the failing heart, while Piezo2 expression and other key ion channels remained unchanged." (PMID 37303604, 2023).
distal arthrogryposis (2 papers, 2019 to 2025). A muscle tissue disease characterized by congenital joint contractures of hand and feet. "Slowing inactivation can increase signaling, as shown for human “gain-of-function” PIEZO1 and PIEZO2 mutations leading to dehydrated hereditary stomatocytosis and distal arthrogryposis, respectively." (PMID 41201821, 2025).
Down syndrome (2 papers, 2024). "Evaluation of central lymphatic flow patterns demonstrated distinct features in individuals with various genetic disorders, such as RASopathies, Down syndrome (trisomy of chromosome 21), and PIEZO1 generalized lymphatic dysplasia." (PMID 38618951, 2024).
erythrocyte diseases (2 papers, 2021 to 2023). "Our work emphasizes the role of the membrane environment in PIEZO1 activity and the need to characterize RBC permeability to assess pathogenicity to PIEZO1 mutants associated with erythrocyte diseases." (PMID 34737711, 2021).
Esophageal Carcinoma (2 papers, 2022 to 2025). A primary or metastatic malignant neoplasm involving the esophagus.
falciparum malaria (2 papers, 2022). "In conclusion, our results provide evidence against a strong protective genetic effect of the PIEZO1 E756del variant on SM susceptibility and underline the need for further studies in populations exposed to falciparum malaria." (PMID 34230590, 2022). "The authors postulate that their results support the notion of PIEZO1 being an important host susceptibility factor for falciparum malaria." (PMID 34230590, 2022).
Glucose intolerance (2 papers, 2023 to 2024). Glucose intolerance (GI) can be defined as dysglycemia that comprises both prediabetes and diabetes. "Activation of the intestinal Piezo1 by its agonist Yoda1 or intestinal bead implantation increased the synthesis and secretion of GLP-1, thus alleviated glucose intolerance in diet-induced-diabetic mice." (PMID 39509292, 2024).
haemoglobinopathies (2 papers, 2022 to 2024). "Our meta-analysis identified several genes associated with Mendelian haemoglobinopathies as sites of ancestral heterogeneity in the genetic architecture of HbA1c (e.g. spectrin [SPTA1], ankyrin [ANK], PIEZO1)." (PMID 39414775, 2024).
hereditary hemolytic anemia (2 papers, 2020 to 2024). "Because Piezo1 is the carrier of Er antigen, Piezo1 mutation is closely related to Er red blood cell antigen, which may explain Piezo1’s connection to neonatal hemolytic anemia." (PMID 38690080, 2024).
idiopathic pulmonary arterial hypertension (2 papers, 2022 to 2023). A sporadic form of pulmonary arterial hypertension (PAH) characterized by elevated pulmonary arterial resistance leading to right heart failure. "Piezo1 is also upregulated in PAECs from idiopathic pulmonary arterial hypertension (iPAH) patients and in animal models of experimental PH." (PMID 38033335, 2023).
idiopathic scoliosis (2 papers, 2021 to 2023). A scoliosis with no known cause. "The NP tissues of Pfirrmann grade I were obtained from the patients with idiopathic scoliosis, but the potential genic changes were possible to influence our results about Piezo1." (PMID 33628392, 2021). "The Piezo1 mRNA expression increased significantly in human NP tissue specimens with IDD contrasted to that in specimens with idiopathic scoliosis." (PMID 33628392, 2021).
injury (2 papers, 2021 to 2025). Damage inflicted on the body as the direct or indirect result of an external force, with or without disruption of structural continuity. "Inhibiting Ca2+ signaling or MAPK will be useful for exploring the mechanism underlying the role of Piezo1 in the promotion of bone trauma repair induced by ultrasound stimulation." (PMID 33692342, 2021).
intracerebral hemorrhage (2 papers, 2025). A cerebrovascular disorder characterized by bleeding into one or both cerebral hemispheres including the basal ganglia and the cerebral cortex. "An experimental study on demyelination following intracerebral hemorrhage (ICH) found that PIEZO1 expression significantly increased 3 h post-ICH injury." (PMID 40703567, 2025).
lung adenocarcinoma (2 papers, 2024). A carcinoma that arises from the lung and is characterized by the presence of malignant glandular epithelial cells. "The objective of the current study was to explore the function and underlying mechanism of PIEZO1 in lung adenocarcinoma (LUAD) cells." (PMID 38494915, 2024).
lymphatic disorders (2 papers, 2024). "Furthermore, whether compound genetic variants in genes in the PIEZO1/ANGPT2/TIE/FOXO1 pathway predispose to lymphatic disorders in humans was not explored here and remains an interesting path for future investigation." (PMID 38747287, 2024).
lymphatic malformation 6 (2 papers, 2021 to 2022). "And also, seven missense mutations in PIEZO1 (Leu939Met, Arg1925Trp, Gly2029Arg, Val2171Phe, Pro2430Leu, Arg2456Cys, and Phe2458Leu) have been demonstrated to lead to lymphatic malformation-6." (PMID 35646098, 2022).
metastatic cancer (2 papers, 2021 to 2024). A carcinoma which has spread from the original site of growth to another anatomic site. "Piezo1 channel activation and Ca2+ influx promote endothelial cell migration during embryonic angiogenesis, suggesting Piezo1's underlying role in cell migration and potential involvement in metastatic cancer." (PMID 39425504, 2024). "Intrinsic apoptosis is inhibited by Bcl-2, which is commonly upregulated in metastatic cancer cells, suggesting the extrusion-related cell death by Piezo1 is less likely to occur in metastatic cancer cells." (PMID 34831037, 2021).
muscular dystrophies (2 papers, 2022 to 2025). "Muscle stem cells (MuSCs) from Piezo1 knockout mice exhibit significantly reduced functional activity, displaying disease phenotypes similar to those of muscular dystrophy, indicating that Piezo1 plays a crucial role in muscle formation." (PMID 41017814, 2025). "It is imperative that future experiments characterise the expression of Piezo1 not only in DMD but other muscular dystrophies." (PMID 35159201, 2022). "Ca2+ regulation plays a crucial role in skeletal muscle maintenance and repair; thus, understanding Piezo1′s function may prove vital when developing therapeutic interventions for muscular dystrophies." (PMID 35159201, 2022). "Although this phenotype could be viewed as beneficial in terms of muscular dystrophy prevention, we must be aware of the potential dangers of an overactive Piezo1 channel." (PMID 35159201, 2022). "Our study shows that Piezo1 is essential for terminal muscle differentiation acting on myoblast fusion, suggesting that Piezo1 deregulation may have implications in muscle aging and degenerative diseases, including muscular dystrophies and neuromuscular disorders." (PMID 35159201, 2022).
myopia (2 papers, 2025). "Notably, Piezo1 channel function inhibition slows myopia progression and partially reduces retinal ROS levels in FDM guinea pigs." (PMID 40880763, 2025). "They found that the Piezo1 channel was activated in the retinas of guinea pigs with form deprivation myopia (FDM) and may play a role in the development of myopia by modulating intraocular reactive oxygen species (ROS) levels." (PMID 40873759, 2025). "Collectively, these findings suggest that enhanced inorganic ion transport, particularly through mechanisms including inward potassium flux and Piezo1 ion channels, may constitute a critical factor in myopia development." (PMID 40880763, 2025). "Weiqi Zhong and colleagues explored the relationship between the Piezo1 channel and myopia." (PMID 40873759, 2025).
pancreatic ductal adenocarcinoma (2 papers, 2023 to 2025). An infiltrating adenocarcinoma that arises from the epithelial cells of the pancreas. "According to Aykut and colleagues, inhibition of Piezo1 unleashes innate immunity against pancreatic ductal carcinoma since Piezo1 is essential for MSDC immunosuppressive functions." (PMID 37762011, 2023). "Nevertheless, a recent investigation has shown that targeting Piezo1 confers protection against pancreatic ductal carcinoma (PDAC) and multi-microbial sepsis, as this channel is essential for myeloid-derived suppressor cell (MDSC) infiltration and immunosuppressive functions." (PMID 37762011, 2023).
parasitemia (2 papers, 2023 to 2024). "We show that both Yoda1 and Jedi2 PIEZO1 activators, have a strong inhibitory effect on parasitemia (in the low micromolar range for Yoda1), reminiscent of the observed reduced multiplication rates in mice carrying PIEZO1 GOF mutations." (PMID 37071200, 2023). "Altogether, these findings indicate that the chemically unrelated PIEZO1 activators Yoda1 and Jedi2 similarly prevent in vitro parasitemia of human RBCs." (PMID 37071200, 2023). "Thus, our results indicated that blockage of Piezo1 with GsMTx4 remarkably prolonged the survival rate but decreased peripheral parasitemia/lung tissue parasite burden and ECM incidence in response to P. berghei ANKA infection." (PMID 38303078, 2024). "Thus, it is likely that additional mechanisms, besides RBC dehydration, may contribute to the observed reduction in parasitemia upon PIEZO1 activation by Yoda1." (PMID 37071200, 2023).
portal hypertension (2 papers, 2025). Increased blood pressure in the portal venous system. "Third, in TAA/CCl4 + PPVL-treated mice, AQP1 expression in LSECs decreased significantly in Piezo1△EC mice compared with Piezo1flox/flox mice, indicating that portal hypertension induced AQP1 expression in LSECs through Piezo1." (PMID 41034523, 2025). "Our study demonstrated that portal hypertension induces Piezo1 activation in peritoneal endothelial cells/LSECs, which gives rise to the accumulation of ascites." (PMID 41034523, 2025). "This indicates that portal hypertension induced AQP1 expression in peritoneal endothelium through Piezo1 in a murine model of liver cirrhosis." (PMID 41034523, 2025). "As a recently identified mechanosensitive cation channel, Piezo1 has been developed rapidly and exhibits great research potential for applications in liver disease." (PMID 41017814, 2025). "Recent studies have also demonstrated the importance of Piezo1 in the liver, particularly, liver diseases." (PMID 41017814, 2025). "In-depth study of these mechanistic associations across cell types will contribute to a more comprehensive understanding of Piezo1’s roles in liver diseases and provide theoretical support for the development of more effective therapeutic strategies." (PMID 41017814, 2025). "Together, these strategies underscore the therapeutic potential of Piezo1 modulation in liver disease and the considerable barriers that remain." (PMID 41017814, 2025). "Accumulating evidence implicates Piezo1-mediated mechanotransduction as a central contributor to liver disease progression, from fibrosis to HCC." (PMID 41017814, 2025). "In particular, the mechanosensitive channel Piezo1 has provided profound insights into the mechanotransduction in liver diseases and therapeutic targeting." (PMID 41017814, 2025). "However, in vivo validation in liver disease models is required to confirm their relevance (e.g., LSEC-specific Piezo1 perturbation in fibrosis or portal hypertension)." (PMID 41017814, 2025). "Thus, modulating Piezo1 expression or activity represents a promising therapeutic avenue for liver disease." (PMID 41017814, 2025). "Future research should validate Piezo1-targeted modulators in appropriate models, uncover tissue-specific regulatory mechanisms of Piezo1 activity, and develop effective therapeutic delivery approaches to leverage Piezo1 as a possible clinical target in liver disease." (PMID 41017814, 2025). "Given the limited literature on targeting Piezo1 for liver disease therapy, future investigations should focus on elucidating Piezo1 mechanisms across various liver disease subtypes, with a particular emphasis on the therapeutic potential of Piezo1 modulation." (PMID 41017814, 2025). "Therefore, the objective of this review article is to provide a comprehensive narrative review of recent advances in research on the ion channel Piezo1 in liver diseases, aiming to offer insights for targeted therapy and drug development." (PMID 41017814, 2025). "Therefore, it is essential to gain a deeper understanding of the mechanisms of Piezo1 in the liver to effectively prevent and treat various liver diseases." (PMID 41017814, 2025). "However, preclinical evaluation of Piezo1 modulators remains limited, and no compounds have yet advanced to registered clinical trials for liver disease indications." (PMID 41017814, 2025).
pregnancy disorder (2 papers, 2025 to 2026). A disorder that is related to pregnancy. "The mechanosensitive ion channel Piezo-type mechanosensitive ion channel component 1 (Piezo1) has recently been shown to act as a shear stress sensor in feto-placental ECs (fpECs), with potential implications for pregnancy disorders." (PMID 39652778, 2025). "Finally, it outlines the therapeutic potential of targeting Piezo1 in related pregnancy disorders and future research directions." (PMID 41789063, 2026).
primary lymphedema (2 papers, 2021 to 2024). A congenital condition that results in swelling in the arms or legs, and can occur during adolescence or adulthood. "In our laboratory, we have seen a patient with primary lymphedema bearing the two missense variants c.1447G>A p.(Val483Met) and c.5891T>C p.(Met1964Thr) in the PIEZO1 gene." (PMID 34946832, 2021). "Prior studies have identified mutations in piezo-type mechanosensitive ion channel component 1 (PIEZO1), angiopoietin 2 (ANGPT2), and tyrosine kinase with Ig-like and EGF-like domains 1 (TIE1) in patients with primary lymphedema." (PMID 38747287, 2024).
primary myelofibrosis (2 papers, 2024 to 2025). Myelofibrosis with myeloid metaplasia is a myeloproliferative disease with annual incidence of approximately 1 case per 100,000 individuals and age at diagnosis around 60 (an increased prevalence is noted in Ashkenazi Jews). "Piezo1 overexpression and altered megakaryopoiesis have also been reported in primary myelofibrosis (PMF), marked by increased MK number and bone marrow stiffness." (PMID 41440018, 2025).
RASopathies (2 papers, 2023 to 2024). "We describe novel variants in several LA genes, including a likely pathogenic variant in PIEZO1, and VOUS in PIEZO1, ITGA9, CELSR1, EPHB4, and TIE1, as well as novel VOUS in RASopathy genes." (PMID 36959127, 2023).
scoliosis (2 papers, 2023 to 2025). A congenital or acquired spinal deformity characterized by lateral curvature of the spine. "In a recent study, bipedal mice that suffered from scoliosis exhibited asymmetric Piezo1 expression due to different compression stress of growth plate area." (PMID 38259612, 2023). "Notably, both conditional PIEZO1 knockout models (Col2a1-CreERT; Piezo1flox/flox) and pharmacological blockade significantly decelerate scoliosis progression." (PMID 40714837, 2025).